LINC00294 (long independently transcribed non-coding RNA 294)
Synonyms: NCRNA00294
Gene: Long non-coding RNA gene on chromosome 11 (33,076,149 to 33,079,454, forward strand). Ensembl gene ENSG00000280798.
Diseases named in the same sentence as LINC00294 in open-access papers:
LINC00294 is named in the same sentence as 2 diseases in open-access papers, as found by Europe PMC text mining. Sharing a sentence is not in itself a finding about the gene and the disease. The quoted sentences say what the papers report.
glioma (4 papers, 2020 to 2024). A benign or malignant brain and spinal cord tumor that arises from glial cells (astrocytes, oligodendrocytes, ependymal cells). "However, whether LINC00294 is implicated in glioma progression through the ceRNA mechanism remains uncertain." (PMID 34777696, 2021). "THBS3, ATP6VOE, and LINC01235 were significantly upregulated while USP32P2, RTN3, and LINC00294 were markedly downregulated in glioma compared to controls." (PMID 32978519, 2020). "To determine the downstream mechanism of LINC00294, we differentially analyzed the miRNA microarray dataset GSE65626 in glioma and identified 50 miRNAs with high expressions in glioma." (PMID 34777696, 2021).
glioblastoma (1 paper, 2021). The most malignant astrocytic tumor (WHO grade IV). "Notably, the NONCODE database indicated that LINC00294 is upregulated in the normal brain tissues, and GEPIA suggests that LINC00294 is notably downregulated in glioblastoma (GBM) tissues." (PMID 34777696, 2021).